YTHDF1 (YTH N6-methyladenosine RNA binding protein F1)
Description:
Specifically recognizes and binds N6-methyladenosine (m6A)- containing mRNAs, and regulates their stability. M6A is a modification present at internal sites of mRNAs and some non-coding RNAs and plays a role in mRNA stability and processing. Acts as a regulator of mRNA stability by promoting degradation of m6A-containing mRNAs via interaction with the CCR4-NOT complex. The YTHDF paralogs (YTHDF1, YTHDF2 and YTHDF3) shares m6A-containing mRNAs targets and act redundantly to mediate mRNA degradation and cellular differentiation. Required to facilitate learning and memory formation in the hippocampus by binding to m6A-containing neuronal mRNAs (By similarity). Acts as a regulator of axon guidance by binding to m6A-containing ROBO3 transcripts (By similarity). Acts as a negative regulator of antigen cross-presentation in myeloid dendritic cells (By similarity). In the context of tumorigenesis, negative regulation of antigen cross-presentation limits the anti-tumor response by reducing efficiency of tumor-antigen cross-presentation (By similarity). Promotes formation of phase-separated membraneless compartments, such as P-bodies or stress granules, by undergoing liquid-liquid phase separation upon binding to mRNAs containing multiple m6A-modified residues: polymethylated mRNAs act as a multivalent scaffold for the binding of YTHDF proteins, juxtaposing their disordered regions and thereby leading to phase separation. The resulting mRNA-YTHDF complexes then partition into different endogenous phase-separated membraneless compartments, such as P-bodies, stress granules or neuronal RNA granules.
Synonyms: DF1; C20orf21; FLJ20391
Tractability: Small molecule: a structure with a bound ligand is known. PROTAC: UniProt records ubiquitination sites on it; ubiquitination databases record sites on it; its protein half-life has been measured.
Gene: Protein-coding gene on chromosome 20 (63,195,429 to 63,216,139, reverse strand). Ensembl gene ENSG00000149658.
Subcellular location: Cytoplasm; Cytoplasm, P-body; Cytoplasm, Stress granule
Gene Ontology:
Molecular function: N6-methyladenosine-containing RNA reader activity; protein binding; ribosome binding; RNA binding
Biological process: mRNA destabilization; organelle assembly; positive regulation of translation; positive regulation of translational initiation; regulation of mRNA stability; stress granule assembly; learning; memory; regulation of antigen processing and presentation; regulation of axon guidance; regulation of long-term synaptic potentiation
Cellular component: cytoplasm; cytoplasmic stress granule; P-body
Genetic constraint (gnomAD): Loss-of-function variants: 17 observed, 49.54 expected, observed/expected ratio (o/e) 0.34, 90% interval 0.23 to 0.51. The upper end of that interval is the gene's LOEUF score, 0.51, which puts it in group 2 of 6, group 1 being the genes least tolerant of losing a copy. Missense variants: 621 observed, 768.28 expected, observed/expected ratio (o/e) 0.81, 90% interval 0.76 to 0.86. Synonymous variants: 313 observed, 300.74 expected, observed/expected ratio (o/e) 1.04, 90% interval 0.95 to 1.14.
Homologues: Orthologues: macaque YTHDF1 (98% identical), chimpanzee YTHDF1 (98% identical), mouse Ythdf1 (94% identical), rat Ythdf1 (94% identical), guinea pig YTHDF1 (93% identical), dog YTHDF1 (93% identical), pig YTHDF1 (86% identical), tropical clawed frog ythdf1 (83% identical), rabbit YTHDF1 (81% identical), zebrafish ythdf1 (78% identical), Drosophila melanogaster Ythdf (37% identical). Paralogues in human: YTHDF3 (70% identical), YTHDF2 (67% identical), YTHDC1 (17% identical).
Diseases named in the same sentence as YTHDF1 in open-access papers:
YTHDF1 is named in the same sentence as 192 diseases in open-access papers, as found by Europe PMC text mining. Sharing a sentence is not in itself a finding about the gene and the disease. The quoted sentences say what the papers report.
hepatocellular carcinoma (93 papers, 2018 to 2026). A malignant tumor that arises from hepatocytes. "YTHDF1 is implicated in driving tumorigenesis, with elevated YTHDF1 linked to poor outcomes in several cancer types including hepatocellular carcinoma, colorectal cancer, and acute myeloid leukemia." (PMID 39325547, 2024). "In hepatocellular carcinoma associated with non-alcoholic fatty liver disease, YTHDF1 can directly target EZH2 mRNA to promote EZH2 translation, leading to the production of cytokine IL-6 in tumor cells." (PMID 38202722, 2023). "Genes related to the m6A modification, such as METTL3 and YTHDF1, are upregulated in hepatocellular carcinoma (HCC) and associated with a worse prognosis." (PMID 36768585, 2023). "Among these m6A readers, YTHDF1 was reported to be associated with hepatocellular carcinoma (HCC) by promoting the Wnt/β-catenin signaling pathway." (PMID 34326699, 2021). "Upregulation of YTHDF1 is intimately associated with poor OS in hepatocellular carcinoma (HCC) and gastric cancer patients." (PMID 34616742, 2021). "As another cytoplasmic m6A reader, YTHDF1 has been reported to be associated with poor prognosis in patients with hepatocellular carcinoma." (PMID 30149601, 2018). "Overexpression of YTHDF1 is associated with the poor prognosis of hepatocellular carcinoma." (PMID 34187307, 2021). "In hepatocellular carcinoma (HCC), the expression of the methylated reader protein YTHDF1 is upregulated and significantly associated with hypoxia-induced autophagy and poor patient prognosis." (PMID 38576024, 2024). "It was shown that high YTHDF1 expression is associated with poor prognosis in hepatocellular carcinoma (HCC) and CRCS." (PMID 39136000, 2024). "The overexpression of YTHDF1 has been widely regarded as a diagnostic and prognostic biomarker in various tumors, particularly in gastric colorectal cancer, prostate cancer, cervical cancer, hepatocellular carcinoma, breast cancer, and non-small-cell lung cancer." (PMID 38202722, 2023). "In hepatocellular carcinoma (HCC), higher expression of YTHDF1 was associated with advanced stages and unfavorable prognosis." (PMID 35197112, 2022). "YTHDF1 is frequently amplified in hepatocellular carcinoma (HCC) tissues and significantly associated with the prognosis of HCC patients." (PMID 34151473, 2021). "For instance, YTHDF1 was proved to be an oncogene in hepatocellular carcinoma (HCC) owing to its overexpression in HCC patients and association with poor prognosis." (PMID 34497675, 2021). "Complementing these findings, the m6A methyltransferase adaptor WTAP contributes to the onset of CD8+ T cell exhaustion in hepatocellular carcinoma (HCC) by increasing PD-1 mRNA translation in a YTHDF1-dependent manner." (PMID 41424859, 2026). "Similarly, YTHDF1 is highly expressed in NASH-associated hepatocellular carcinoma (NASH-HCC) and promotes tumorigenesis." (PMID 41403953, 2025). "It has been reported that YTHDF1 as a potential therapeutic target for hepatocellular carcinoma (HCC) promotes cancer progression." (PMID 40097750, 2025). "For instance, HIF-1α has been shown to directly stimulate the transcription of YTHDF1, thereby facilitating hepatocellular carcinoma (HCC) autophagy and malignancy by enhancing the translation of ATG2A and ATG14." (PMID 40136363, 2025). "Silencing of YTHDF1 inhibits autophagy, as well as the proliferation, migration, and invasion ability of hepatocellular carcinoma cells." (PMID 38576024, 2024). "YTHDF1 promotes cancer stem cell renewal and resistance to tyrosine kinase inhibitors in hepatocellular carcinoma (HCC), which enhances the stability and translation of m6A-modified NOTCH1 mRNA, leading to increased expression of NOTCH1 target genes." (PMID 39185313, 2024). "For example, HIF-1α was found to not only promote the glycolytic process but also enhance the expression of YTHDF1/2 in hepatocellular carcinoma (HCC) and lung squamous cell carcinoma (LUSC), respectively, leading to cancer cell spread." (PMID 39033180, 2024).
hepatocellular carcinoma (continued). "For instance, in a mouse model of hepatocellular carcinoma, knockdown of YTHDF1 significantly inhibited autophagy and tumor growth." (PMID 38576024, 2024). "In this study, we developed photosensitive dual-targeting nanoparticles for delivering short interfering RNAs (siRNAs) that target the m6A reader YTHDF1 to treat hepatocellular carcinoma by modulating epigenetics and the immune response." (PMID 38898486, 2024). "Analysis of The Cancer Genome Atlas database revealed that YTHDF1 expression is significantly upregulated in hepatocellular carcinoma (HCC) and positively correlates with pathological stage." (PMID 39445003, 2024). "Previous studies have shown that YTHDF1 and METTL3 upregulation is associated with poor survival in hepatocellular cancer." (PMID 38436011, 2024). "Studies have shown that in the hypoxic environment generated by circumstances, such as hepatocellular carcinoma, breast cancer, and islet transplantation, Yth m6A RNA-binding protein 1 (YTHDF1) appeared higher expression relative to normal tissues." (PMID 36675257, 2023). "YTHDF3 interacts with YTHDF1 to facilitate the translation of hepatocellular carcinoma-targeting mRNAs." (PMID 38102645, 2023). "A previous study indicated that YTHDF1 upregulated autophagy-related genes to promote hepatocellular carcinoma (HCC) progression." (PMID 37259333, 2023). "The promotion of upregulated cirMAP2K4 sponged hsa-miR-139-5p to increase YTHDF1 activity, resulting in stimulating development and progression of hepatocellular carcinoma." (PMID 36875073, 2023). "It has been shown that YTHDF1 expression upregulated in a HIF-1α-dependent manner by promoting transcription in human hepatocellular carcinoma." (PMID 36675257, 2023). "YTHDF1 also functions in hepatocellular carcinoma by promoting the translation of SLP2 through an m6A-dependent mechanism in conjunction with METTL3." (PMID 38202722, 2023). "The expression levels of YTHDF1 had a tight correlation with cancers proved by many researches, such as LC, hepatocellular carcinoma (HCC), and colorectal cancer (CRC)." (PMID 36261786, 2022). "For example, Hypoxia was found to upregulate YTHDF1 expression in a HIF-1α dependent manner in hepatocellular carcinoma." (PMID 35197112, 2022). "A number of studies had shown that YTHDF1 was overexpressed in various cancers, including colorectal cancer, hepatocellular carcinoma, and breast cancer, and was closely related to the increased risk of these cancers." (PMID 36072379, 2022). "High YTHDF1 expression is associated with poor prognosis in hepatocellular carcinoma (HCC) and CRC." (PMID 35509101, 2022). "Higher expression of YTHDF1 is related to worse prognosis in patients with hepatocellular carcinoma." (PMID 33791305, 2021). "The aberrant expression and pro-oncogenic role of YTHDF1 have been demonstrated for several types of cancer such as hepatocellular carcinoma, colorectal cancer, lung cancer." (PMID 33317545, 2020). "YTHDF1 is upregulated in ovarian cancer, lung cancer, hepatocellular carcinoma, and colorectal cancer." (PMID 32582536, 2020). "Stabilization of FOXO3 mRNA by YTHDF1 is impaired in hypoxic sorafenib‐resistant hepatocellular carcinoma due to downregulation of the RNA methyltransferase METLL3." (PMID 32368828, 2020). "Here, 13 differentially expressed m6A methylation regulators were confirmed in 374 hepatocellular carcinoma (HCC) patients, among which RBM15, YTHDC1, YTHDF1, and YTHDF2 were significantly variant in different stages and grades." (PMID 32974160, 2020). "Previous studies have demonstrated that YTHDF1 and YTHDF2 are highly expressed in hepatocellular carcinoma, affecting cell cycle and metabolism of tumor cells, and the prognosis of high YTHDF1 expression in patients was poor." (PMID 32631107, 2020).
hepatocellular carcinoma (continued). "In carcinomas, such as hepatocellular carcinoma, YTHDF1 was shown to increase the expression of SNAIL, which is the master regulator of epithelial-mesenchymal transition program associated with increased cell invasion." (PMID 33317545, 2020). "For instance, it's been reported that METTL3 partners with YTHDF1 to boost hepatocellular carcinoma progression, triggers the PI3K/AKT signaling pathway to enhance prostate cancer growth, and plays roles in chemoresistance across various cancers like oral cancer, acute myeloid leukemia, and more." (PMID 38112021, 2023). "In addition to its primary function in promoting protein translation, YTHDF1 was recently reported to promote the stability of mRNAs via m6A modifications in multiple cancers, such as gastric cancer (GC), hepatocellular carcinoma (HCC) and cervical cancer." (PMID 36551532, 2022). "In addition, YTHDF1 has also been confirmed to have carcinogenic effects in many digestive system tumors including gastric cancer, hepatocellular carcinoma and colorectal cancer." (PMID 36324565, 2022). "YTHDF1 has been reported to be upregulated in expression in many tumors, such as colorectal cancer and hepatocellular carcinoma, and may be an essential oncogene." (PMID 35069679, 2021). "In addition, they also found that the up-regulated M6A regulatory factors METTL3 and YTHDF1 were important factors leading to the poor prognosis of hepatocellular carcinoma." (PMID 33428597, 2021). "In hepatocellular carcinoma tissues, YTHDF1, KIAA1429 and WTAP are significantly upregulated." (PMID 34794452, 2021). "YTHDF1 can reflect the malignant degree of hepatocellular carcinoma and has prognostic value." (PMID 33796449, 2021). "The expression of YTHDF2 is up‐regulated in hepatocellular carcinoma, pancreatic cancer, etc, the expression of YTHDF1 is up‐regulated in colorectal cancer, hepatocellular carcinoma, ovarian cancer, lung cancer, etc, and both YTHDF1 and YTHDF2 are independent risk factors for OS." (PMID 32808488, 2020). "The relationship between YTHDF1 and cancer has been reported in hepatocellular carcinoma." (PMID 32258108, 2020). "Studies have reported that YTHDF1 is an oncogene that is highly expressed and positively correlates with the pathology stage in hepatocellular carcinoma (HCC)." (PMID 36999016, 2023). "YTHDF1 expression is significantly upregulated in hepatocellular carcinoma (HCC) and exhibits a positive correlation with pathological stages." (PMID 38072944, 2023). "In line with this notion, the expression of m6A reader YTHDF1 is significantly correlated with hypoxia-induced autophagy in patients with hepatocellular carcinoma (HCC)." (PMID 37753070, 2023). "For instance, a recent data analysis suggested that circMAP2K4 interacted with miR-139-5p, which contributed to the target gene, YTHDF1, expression in hepatocellular carcinoma (HCC)." (PMID 35843942, 2022). "In hepatocellular carcinoma (HCC), YTH domain containing family protein-1 (YTHDF1) facilitates EMT in part by increasing translation of FZD5 and activating canonical β-catenin signaling." (PMID 34604862, 2021). "It has been reported that YTHDF1 could regulate cell cycle progression in hepatocellular carcinoma." (PMID 34434939, 2021). "Specifically, studies have shown that YTHDF1 is high-expressed in multiple malignancies and promotes the progression of colorectal carcinoma, ovarian cancer, gastric cancer, non-small cell lung cancer, and hepatocellular carcinoma through a range of oncogenic mechanisms." (PMID 34088349, 2021). "Moreover, it was found that combined levels of METTL3 and YTHDF1 could reflect the malignancy state and prognosis of hepatocellular carcinoma (HCC)." (PMID 33816266, 2021). "YTHDF1, induced by HIF-1α, promotes hypoxia-induced autophagy and hepatocellular carcinoma malignancy through m6A-modified ATG2A and ATG14 dependency." (PMID 40251202, 2025).
hepatocellular carcinoma (continued). "The YTHDF1/EIF3C axis is involved in the invasion process in ovarian cancer; EIF3H participates in the invasion of hepatocellular carcinoma and the EIF4A3/FLOT1 pathway promotes invasion and tumor proliferation in lung adenocarcinoma." (PMID 40705973, 2025). "In hepatocellular carcinoma (HCC), METTL3 depletion promoted the LC3-II accumulation by reducing the stability of FOXO3 mRNA through a YTHDF1-dependent mechanism." (PMID 36517820, 2022). "YTHDF1 mediates the translation of Snail mRNA with increased m6A in CDS, but not in the 3′ UTR, promoting cancer cell migration, invasion, and EMT in hepatocellular carcinoma." (PMID 36358640, 2022). "In hepatocellular carcinoma, HIF-1α promotes the expression of YTHDF1 by binding to the promoter of YTHDF1, and then combines with ATG2A and ATG14 by m6A modification to promote their translation and malignant progression of cancer." (PMID 35022030, 2022). "In sorafenib-resistant hepatocellular carcinoma, METTL3 was significantly down-regulated and could promote m6A modification of FOXO3 3’UTR increasing its stability via recruiting YTHDF1, thereby enhancing sorafenib resistance of HCC." (PMID 35144642, 2022). "For example, the high expression of YTHDF1 and YTHDF2 was related to the poor prognosis of patients with hepatocellular carcinoma, indicating that it promotes proliferation and inhibits invasion and metastasis." (PMID 33779693, 2021). "YTHDF1 (m6A “reader”) can be used to predict poor prognosis in breast cancer and promotes FDZ5 translation, leading to hepatocellular carcinoma progression." (PMID 33791305, 2021). "For example, sublethal heat treatment increases EGFR m6A modification near the 5′UTR region and promotes its binding to YTHDF1, thereby enhancing the translation of EGFR mRNA and promoting hepatocellular carcinoma progression." (PMID 34026852, 2021). "More recent work suggests that IGF2BP1, YTHDF1 and YTHDF1 mainly function as oncogenes in multiple cancer types, including colorectal cancer, hepatocellular carcinoma (HCC), gastric cancer, lung cancer, AML, pancreatic cancer, OC, bladder cancer, prostate cancer and melanoma." (PMID 34895230, 2021). "Recently, a study reported that m6A reader YTHDF1 could promote hypoxia-induced autophagy, which in turn facilitated the development of human hepatocellular carcinoma (HCC)." (PMID 34315538, 2021). "YTHDF1 plays a crucial part in the regulation of cell cycle and metabolism of hepatocellular carcinoma, while YTHDF2 exerts an inhibitory effect on hepatocellular carcinoma cells." (PMID 34794452, 2021). "Patients in the low METTL3/YTHDF1 group have a better prognosis, so the combination of METTL3 and YTHDF1 serves as a biomarker reflecting the malignancy and prognostic outcome of hepatocellular carcinoma." (PMID 34660577, 2021). "For example, in hepatocellular carcinoma (HCC), YTHDF1 recognizes the m6A mark on SLC7A11 mRNA to enhance the inhibition of ferroptosis, and in hepatic stellate cells, YTHDF1 also recognizes m6A mark on the BECN1 mRNA, enhancing ferritinophagy to induce ferroptosis." (PMID 37229485, 2023). "YTHDF1 can affect the progression of ovarian, breast and small cell lung cancers, and it can drive hypoxia-induced autophagy in hepatocellular carcinoma, but no relevant studies have been reported on BLCA." (PMID 37108067, 2023). "LINC00665 can modulate 11 mRNAs by regulating m6A enzymes YTHDF1, IGF2BP1, and IGF2BP2 in hepatocellular carcinoma (HCC)." (PMID 38351139, 2024). "In primary hepatocellular carcinoma (HCC), METTL3 adds m6A modification to the 3′-UTR of FOXO3 mRNA, a negative regulator of autophagy, increasing its mRNA stability in a YTHDF1-dependent manner." (PMID 39686999, 2024). "In this section, the functions and molecular mechanisms of YTHDF1 in GC, CRC, and hepatocellular carcinoma (HCC), the three most common GI cancers, are discussed." (PMID 35884552, 2022).
hepatocellular carcinoma (continued). "In hepatocellular carcinoma (HCC) cells, the depletion of METTL3 can promote autophagy by inducing autophagy-related gene transcription and leading to forkhead box protein O3 (FOXO3) degradation via a YTHDF1-dependent pathway." (PMID 36632456, 2023).